CD4 (CD4 molecule)
Diseases named in the same sentence as CD4 in open-access papers (continued):
Sharing a sentence is not in itself a finding about the gene and the disease.
atherosclerosis (continued). "Atherosclerosis is a chronic inflammatory disease involving activation of variety of immune cells including T lymphocytes, specifically CD4+ T cells with a T helper cell 1 (Th1) phenotype." (PMID 23029000, 2012). "Aim of this work was to investigate the relationship between circulating CD4+T-cell subsets and atherosclerosis." (PMID 23130116, 2012). "CD4+CD25+ Tregs also play an important role in the pathogenesis of atherosclerosis and are expected to be a novel therapeutic target to attenuate atherosclerosis and stabilize vulnerable plaques." (PMID 22888436, 2012). "With regards to immune cell subtypes, CD4+ T cells are present in the highest concentration in the earliest phases of atherosclerosis." (PMID 23304456, 2012). "The induction of atherosclerosis appears to be CD4+ T cell dependent and dissociated from the magnitude of lung inflammation or fibrosis associated with inhaled asbestos." (PMID 18795166, 2008). "We examined the mechanisms by which CCR4 deficiency accelerates early atherosclerosis by focusing on changes in systemic T cell responses, including those involving CD4+Foxp3+ Tregs and CD4+Foxp3- non-Tregs, in peripheral lymphoid tissues." (PMID 40608058, 2025). "However, circulating and atherosclerotic plaque Tregs decline in the later stage of atherosclerosis, whereas total CD4+ effector T cells and splenic Tregs expand with increased atherosclerotic lesion size." (PMID 41143276, 2025). "Moreover, research has demonstrated the involvement of PKM2 in the metabolic reprograming of CD4+ T cells and its role in HHcy-accelerated atherosclerosis." (PMID 39898976, 2025). "Intravenous administration of anti-CD3–specific antibodies effectively suppresses effector T cell immune responses and reduces atherosclerosis in mice by inducing TGF-β–producing CD4+CD25+ LAP+ Tregs, which in turn inhibit experimental autoimmunity in a TGF-β–dependent manner." (PMID 39817455, 2025). "Additionally, shikonin (SKN), a natural naphthoquinone, has been shown to attenuate HHcy-induced atherosclerosis in ApoE−/− mice by inhibiting metabolic reprogramming in CD4+ T cells." (PMID 39898976, 2025). "Similarly, IS contributes to oxidative stress and inflammation, resulting in endothelial dysfunction, atherosclerosis, and reduced proliferation of CD4 + T-cells." (PMID 40292469, 2025). "B cells, T cells (including clonally expanded CD4+ cells with heightened proinflammatory and CD8+ cells with cytotoxic properties), granzyme B, TNF-α, IL-6, and TLR 2 and 4 all contributed to the inflammatory processes underlying atherosclerosis." (PMID 40046046, 2025). "Interestingly, DCs, however, appear to maintain their capacity to prime CD4+ T cells and regulate their response in experimental atherosclerosis in mice, even in the presence of hypercholesterolemia." (PMID 38397127, 2024). "Naive CD4+ T cells play a role in the development of atherosclerosis." (PMID 39610972, 2024). "Similarly, prior results from MESA identified a pattern of higher memory and lower naive CD4+ cells with type 2 diabetes and subclinical atherosclerosis." (PMID 38596669, 2024). "Additionally, the recognition of the ApoB100 component in oxidized LDL by CD4+ T cells aids in the progression of atherosclerosis through cytokine-mediated inflammation." (PMID 39456811, 2024). "In addition, the fact that B2 cell depletion was correlated with the reduction of activated splenic CD4+ T cells, T cells proliferation, and diseased T cells suggests that B2 cells through a T cell-dependent mechanism exacerbate atherosclerosis." (PMID 39399488, 2024). "Notably, blocking the CCL5-CCR5 interaction leads to reduced infiltration of effector CD4+ T cells into aorta explants, underscoring the importance of these interactions in atherosclerosis progression." (PMID 38781301, 2024).
atherosclerosis (continued). "Consequently, Aza-induced autologous CD4+ T cells offer a promising solution for alleviating atherosclerosis by ensuring a sufficient number of Tregs and minimising the risk of immune rejection." (PMID 39304654, 2024). "However, inflammatory CD4+ effector T cells increase and Treg cells decrease in lesions, and thus disrupt the balance of these two, accelerating the progression of atherosclerosis." (PMID 38774746, 2024). "Additionally, CD8+CD25+ T cells, identified as having a suppressive phenotype, were shown to repress splenic CD4+ T cells and reduce atherosclerosis in recipient mice." (PMID 39766344, 2024). "Th17 cells are the third largest subpopulation of CD4+ T cells in atherosclerosis." (PMID 38774746, 2024). "This study investigated whether the transfer of naive CD4+ T cells, induced to differentiate into Tregs by using Aza in vitro, could suppress atherosclerosis in mice." (PMID 39304654, 2024). "Additionally, analyzing CD4+ T cell subgroups using multi-parameter/multi-color flow cytometry and their correlation with atherosclerosis has been studied." (PMID 39610972, 2024). "Furthermore, homocysteine-activated CD4+ T cells were found to increase pyruvate kinase muscle isoenzyme 2 (a key rate-limiting enzyme in glycolysis), thereby accelerating arteriocoronary atherosclerosis." (PMID 39723414, 2024). "On the other hand, CD4+ T cells are the key regulator of adaptive immunity in atherosclerosis." (PMID 38774746, 2024). "While previous research evaluated the effect of fatty acids on CD4+ T cell function during or after activation, interactions between fatty acids and CD4+ T cells relevant for atherosclerosis can already occur in the circulation, when the cells are in a non-activated state." (PMID 38558932, 2024). "Similarly, we examined the distributions of CD4+ T cells along pseudotime separately for atherosclerosis and NC using Monocle2." (PMID 37706320, 2023). "Compared to Treg numbers and their functional characteristics, the imbalance of Treg cells with effector immune cell subsets (such as Th1, Th2, CD4+CD28null, and Th17) appears to be a more important mechanism contributing to pro-inflammatory responses in atherosclerosis and plaque instability." (PMID 37763334, 2023). "CD4+ T cell subpopulations can differentially impact atherosclerosis progression and ACS events." (PMID 37109221, 2023). "Furthermore, CD4+ T regulatory cells are supposed to have an atheroprotective role via IL-10 and TGFβ secretion, however, in the late stage of atherosclerosis, they can convert into pro-atherogenic ex-T regulatory cells." (PMID 38138958, 2023). "Distinct influences on atherosclerosis have been observed from different subgroups of CD4+ T cells." (PMID 37928762, 2023). "However, the proportion of CD4 naive T cells, regulatory Tregs T cells, activated dendritic cells, resting mast cells and neutrophils in atherosclerosis tissue was significantly higher than that in normal tissue." (PMID 37173673, 2023). "CD4+ T cells could proliferate and secrete cytokines to promote atherosclerosis when restimulated with low-density lipoprotein cholesterol (LDL-C) and apolipoprotein B (ApoB)." (PMID 37461090, 2023). "As a whole, the depletion of CD4+ T cells protects against atherosclerosis." (PMID 37681883, 2023).
atherosclerosis (continued). "In contrast, CCL17 + DCs, another subtype of DCs, can prime antigen-specific T cell responses to increase the concentration of CD4 + T cells and then promote atherosclerosis by inhibiting Treg differentiation and promoting Treg apoptosis by regulating the Jak/Stat signaling pathway." (PMID 37163428, 2023). "In contrast, proinflammatory CD4+ CD28null T cells predicted a poor outcome in atherosclerosis." (PMID 36855107, 2023). "Immunocyte infiltration analysis on the GSE40231 dataset showed that the proportions of CD4 memory resting T cells, gamma delta T cells, M0 macrophages, M1 macrophages and activated mast cells in atherosclerosis tissue were significantly lower than those in normal tissue." (PMID 37173673, 2023). "Furthermore, anti-inflammatory/inflammation-regulatory genes (like IL7R, ANXA1, and KLRB1) and pathways (like regulation of IL-2 production) were decreased in CD4+ T cells (T_1, T_2, and T_3) from atherosclerosis compared with those from NC." (PMID 37706320, 2023). "CD4 + T cells receive antigens presented by antigen-presenting cells and differentiate into different Th cells (Th1, Th2, Th9, Th17, Th22, Tfh) and Treg cells through immune responses, whose role in atherosclerosis is multifaceted." (PMID 37173646, 2023). "Our results indicate the most important cytokines identifying obstructive CAD are IL-1β, which was indeed chosen as the target of the first anti-inflammatory trial to treat atherosclerosis and IL-12, that drives the CD4 + Th1 response, which is pro-atherogenic." (PMID 37004526, 2023). "Furthermore, Th1 cells are the main type of CD4+ T cells in AS, which produce a large number of pro-inflammatory cytokines, while Th2 cells can produce IL-13 and IL-5 to antagonize atherosclerosis." (PMID 36969166, 2023). "In addition to Dpp4, there was an upregulation of a number of inflammation‐related genes including Card8, Card16, Gzma, Prf1, Il2rg, Il32, Cd52, and Ccl4 in CD4+ T cells isolated from patients with atherosclerosis." (PMID 36683148, 2023). "In addition, single-cell transcriptomics showed that T cells were the most abundant population of immune cells in human carotid atherosclerotic plaques, suggesting that CD4+ T cells were involved in atherosclerosis." (PMID 37461090, 2023). "Our findings, in combination with those of previous studies, indicated that the regulation of APOAI to CD4+ T cells may be another key step and mechanism for anti‐atherosclerosis in CAD." (PMID 36988256, 2023). "Additionally, proinflammatory CD4+ CD28null T cells and dysfunctional TREM2- SPP1+ foamy macrophages, which were associated with atherosclerosis progression and poor prognosis, were expected to be potential therapeutic targets for future precision medicine." (PMID 36855107, 2023). "Considering that activated CD4+ T cells play a role in atherosclerosis by infiltrating atherosclerotic plaques, Zakharova and colleagues investigated whether sEV derived from human CD4+ T cells may affect cholesterol production/distribution on monocytes." (PMID 37762077, 2023). "Thus, our data suggest that atherosclerosis is characterized by an autoimmune component driven by autoreactive CD4+ T cells." (PMID 38665903, 2023). "In an animal experiment, cytokine therapy with IL-2/anti-IL-2 monoclonal antibody complexes could attenuate the development and progression of atherosclerosis by increasing CD4+CD25+Foxp3+ regulatory T cells in apolipoprotein E-deficient mice." (PMID 36299596, 2022). "Our findings may shape a novel strategy for platelet-targeted PF4–TGFβ duet intervention of CD4+ T cell immunity and inflammation in the clinical settings of CD4+ T cell disorders, such as atherosclerosis." (PMID 35437611, 2022). "Sc-RNA-seq research found a higher CXCR3 expression level in circulating CD4+ T cells in symptomatic atherosclerosis patients compared to asymptomatic atherosclerosis patients, indicating that these cells can be activated and recruited into plaques to aggravate the disease." (PMID 36685487, 2022).
atherosclerosis (continued). "We review the mechanisms of CD4+ T subsets, i.e., helper T17 (Th17) cells and regulatory T cells (Tregs), in regulating atherosclerosis, focusing on the role of interleukin (IL)-17, IL-10, and other cytokines in this disease and the factors influencing the effects of these cytokines." (PMID 36211578, 2022). "The patient was diagnosed more than ten years after being infected, when he had an advanced disease stage (CD4 165 cells/mm3 and viremia 16,300 copies/mL), which could have played a part in early atherosclerosis development." (PMID 36553155, 2022). "However, the complex regulatory network responsible for the CD4+T immune responses leading to the development of atherosclerosis, and the subsequent cardiovascular diseases, especially LEASO, remains insufficiently understood." (PMID 35757718, 2022). "Patients with high risks for atherosclerosis such as those with a family history of MI were revealed to have reversed and/or prevented atherosclerosis or CVD as their Treg CD4+ T-cells were obtained and transduced with lentivirus for CAR expression before reintroduced into their circulation." (PMID 36361845, 2022). "Evidence for relevant implications of these cells in cardiovascular diseases exist in atherosclerosis, where Th1 and Th17 cells emerge in the development of atherosclerosis when autoreactive CD4+ T cells are stimulated with ApoB peptides in an environment of inflammatory cytokines." (PMID 35845058, 2022). "Here, we reviewed the mechanisms of Th17 cell- and Treg-mediated atherosclerosis in existing CD4+ T cell subpopulations, thereby providing targets for atherosclerosis treatment and a feasible direction for research on the inhibition of atherosclerosis progression through immunomodulation." (PMID 36211578, 2022). "Despite these discrepancies in T helper contribution to the disease, the adoptive transfer of CD4+ T cells has been shown to aggravate atherosclerosis in immunodeficient Apoe–/– mice, while the transfer of other specific subsets, such as the immunosuppressive Tregs, limits plaque progression." (PMID 35966516, 2022). "Thus, almost all CD4+ T cell hybridomas reported in atherosclerosis belong to T helper 1 (Th1), although many other T cells are found in atherosclerotic lesions in situ." (PMID 35269559, 2022). "In addition, in mouse models of atherosclerosis, the disease seems to be driven by IFNγ-producing CD4 T cells upon antigen recognition on DC/macrophages localized in the arterial wall." (PMID 35903540, 2022). "For example, atherosclerosis represents a chronic inflammatory disease of arterial walls with the involvement of CD4+ T cells, and exosomes shed locally by these cells could exaggerate oxidative stress and promote endothelial dysfunction." (PMID 36211827, 2022). "A relatively higher level of CD4 T cells was shown to ameliorate atherosclerosis." (PMID 35978314, 2022). "Then, we analyzed the percentage of CD4+T cells in different stages of atherosclerosis." (PMID 33981738, 2021). "Of note, these ApoB100-autoreactive CD4+ T cells are mainly comprised FoxP3+ Tregs in healthy individuals, whereas in patients with subclinical atherosclerosis, they are comprised less of Tregs and more of T-bet+ Th1 and retinoic-acid receptor-related orphan receptor (ROR)-γt+ Th17 cells." (PMID 33805071, 2021). "CD4+ T and CD8+ T cells were associated with increased atherosclerosis in ApoE−/− mice." (PMID 33841393, 2021). "Besides tumors and chronic infections, CD4+GranzB+CTLs were also found in some autoimmune or chronic inflammatory diseases, including RA, atherosclerosis, Graves’ disease, sporadic inclusion body myositis, and Wegener’s granulomatosis." (PMID 34641948, 2021).
atherosclerosis (continued). "Previous study revealed that the expression of CD4 might be increased during inflammation and thrombosis, altering the immune cell-mediated response and leading to atherosclerosis." (PMID 34285702, 2021). "Yet, it is unclear whether AIRE controls the expression of ApoB and the autoimmune CD4+ T cell response in atherosclerosis." (PMID 35097028, 2021). "Notably, adoptive transfer of CD4+CD25+ Tregs abrogated the detrimental effects on atherosclerosis observed in Apoe−/− mice with the CD80/CD86–CD28 pathway deficiency." (PMID 34945203, 2021). "Indeed, swiprosin-1 was also found to be in many other immune cells including CD8+ T, CD4+ T lymphocytes, NK cells, and mast cells, which have emerged as critical drivers and modifiers of the pathogenesis of atherosclerosis." (PMID 34759279, 2021). "These associative findings argue against a solely protective role of Tregs and may be partially explained by the appearance of Treg-like CD4+ T cells that express FoxP3 and pro-inflammatory cytokines in advanced atherosclerosis." (PMID 33669769, 2021). "Since this cell population comprises different effector cells, including Th1, Th2, Th17 and Treg cells, that can have opposing effects on atherosclerosis, we did a qPCR analysis and screened the spleen samples for the signature markers of different CD4+ T cell subtypes." (PMID 34868038, 2021). "T cells and particularly the CD4+ lineage are important players in atherosclerosis pathogenesis and the influx of CD4+ T cells to the vascular walls may be regulated by alterations to cytoskeleton dynamics as a result of aberrant expression of miR-142-3p." (PMID 33483751, 2021). "CD4+ T cells populations also influence cholesterol-related diseases, such as atherosclerosis." (PMID 33505215, 2021). "To explore whether rSj-Cys reduces the development of atherosclerosis by stimulating Treg, we detected the Treg-expressed CD3ε, CD4, and CD25 on the surface and the intracellular expression of Foxp3 in splenocytes." (PMID 34901005, 2021). "Decreasing the number of CD4+CD25+Foxp3+ Tregs was related to the progression of atherosclerosis." (PMID 34901005, 2021). "In addition, the abatacept-mediated inhibition of CD80/CD86-CD28 interactions reduced atherosclerosis in ApoE3*Leiden mice by preventing the activation of CD4+ T cells." (PMID 32872393, 2020). "1,5-AG can predict CD8+T and CD4+T cell modifications related to atherosclerosis." (PMID 32090117, 2020). "In a second experiment, in which the number of rounds was increased to three, we found that the combination of VitD and Dexa induced the highest percentage of FOXP3+ CD4+ T cells when injected either in absence or presence of the atherosclerosis-relevant antigen LDL." (PMID 32395119, 2020). "Recognizing that, in advanced atherosclerosis, a shift toward expression of CD4 + Th2 lymphocytes over Th1 (mainly proinflammatory) happens, suggesting the adaptation of the immune system to less proinflammatory, is important for the further research on the topic." (PMID 32443695, 2020). "ApoE−/− mice lacking CD4+ T cells were found less susceptible to atherosclerosis compared with wild-type mice, and transfer of CD4+ T cells to immunodeficient ApoE−/− mice significantly promoted atherosclerosis." (PMID 32460698, 2020). "IL-1β signaling was reported to promote a Th17 response in CD4+ T cells in atherosclerosis." (PMID 32373127, 2020). "In addition to transformation of CD4+ T cells, MDV causes atherosclerosis by disturbing the lipid metabolism in infected chickens, which can be inhibited by vaccine-induced immunity." (PMID 30971474, 2019). "In addition, we demonstrated that fimasartan reduced the size of pulps, splenic macrophages, and CD4+ T cells in CA-injured mice with ameliorated atherosclerosis." (PMID 31307370, 2019).